INS (insulin)
Diseases named in the same sentence as INS in open-access papers (continued):
Sharing a sentence is not in itself a finding about the gene and the disease.
tumor (continued). "This case metastasized to the liver, Case 9, 2 years after enucleation, which was predominantly solid pattern and showed less insulin and moderately CgA staining in 10% of tumor cells and diffuse strong SPY staining." (PMID 32020844, 2020). "We found that SFRP2 promoter methylation was positively correlated in tumor area with insulin and HOMA-IR but negatively correlated with HDL-c." (PMID 32517740, 2020). "Insulin lipohypertrophy shows a tumor-like swelling of fatty tissue at the injection site due to the lipogenic effect of insulin." (PMID 32056035, 2020). "Fatty acids are potent swelling and uncoupling agents that can stimulate insulin secretion and glucose/glutamine consumption thus making it appear as if tumor cells can metabolize fatty acids for energy." (PMID 32219096, 2020). "Akt (Protein kinase B, PKB) is a serine/threonine kinase that plays a key role in regulating cell survival, insulin signaling, angiogenesis and tumor formation." (PMID 32489562, 2020). "Most studies evaluated tumor and serum factors in relation to proliferative activity or insulin signaling, and some factors were affected by metformin as expected." (PMID 32842547, 2020). "This has a direct effect by increased binding of insulin to the tumour cell’s insulin-receptor and an indirect effect by increasing the concentration of free insulin-like-growth-factor-1 (IGF-1), resulting in increased tumour growth." (PMID 32210471, 2020). "(c) Refined grain has a higher digestibility than whole grain, resulting in glycemic overload, higher plasma insulin concentration and compensatory increases in insulin‐like growth factor I, an important mitogenic stimulant of tumor cell growth in vitro." (PMID 30680179, 2019). "In other words, periphery IR is a common characteristic of various tumor-bearing hosts, but after surgical removal of the tumor the level of insulin sensitivity has been restored." (PMID 31019893, 2019). "Tumor glucose uptake and oxidation were both modulated by circulating insulin concentrations and normalized by insulin sensitization: high fat feeding increased, and CRMP decreased, both parameters." (PMID 31867105, 2019). "TrxR1 activity in gastric cells or tumor tissues was determined by the endpoint insulin reduction assay." (PMID 31113439, 2019). "The serum insulin decreased in the tumour-bearing group (W), starting on the 14th day, and became more prominent following the 21st day of the experiment." (PMID 30975087, 2019). "Even in the presence of the growing tumor, the endocrine cells, notably insulin-secreting cells, seem to maintain their function." (PMID 30965637, 2019). "In this study, we uncover the Tmem127 tumor suppressor as an unsuspected regulator of insulin signaling and lipogenesis." (PMID 31624249, 2019). "Metformin attenuates the systemic biological effect of IR/IGF on tumor-promoting signaling by improving insulin sensitivity and suppressing liver glucose output, which leads to reduced levels of systemic circulating insulin." (PMID 31703648, 2019). "Metformin suppresses the effect of high-energy diet in promoting the growth of tumor in xenografts mice model (MC38 colon carcinoma cells) by reducing the insulin level and FASN while inactivating the Akt protein." (PMID 31831021, 2019). "To examine the impact of the reduction in plasma insulin on tumor growth and metabolism, we infused insulin subcutaneously to match plasma insulin concentrations in 5-h fasted dapagliflozin-treated mice to those measured in untreated HFD controls." (PMID 31867105, 2019). "The INS-1 tumor cell line showed increased insulin secretion, but the HIT-T15 cell line displayed greater uptake of E2 and ER after transient ER expression, with faster turnover." (PMID 30790128, 2019). "KGDs also reduce insulin levels, thereby limiting glycolysis at its most proximal step and depriving tumor cells and their stroma of important nutritional and hormonal support." (PMID 31242205, 2019).
tumor (continued). "Biological mechanisms linking excess adiposity to poor prognosis tumor characteristics include local and systemic alterations to inflammatory markers, steroid hormones, cytokines/adipokines, insulin, and insulin-like growth factors (IGFs)." (PMID 31602394, 2019). "In the tumour sphere culture system, insulin is an essential factor to promote the growth and stemness for enriching stem cells." (PMID 30770752, 2019). "Specifically, it is known that low serum APN levels are associated with hyperinsulinemia, which has been demonstrated to promote the proliferation of tumor cells acting as a growth factor through insulin and IGF-I receptors." (PMID 31212761, 2019). "Secondly, a substantial part of the insulin effect is mediated by paracrine signaling in the tumor micro-environment between adjacent adipocytes, fibroblasts, and the epithelial cancer cell." (PMID 31703648, 2019). "EGF, b-fibroblast growth factors (b-FGF) and insulin are the three major components in our sphere-formation pelletizing system, which also exist in the tumor microenvironment." (PMID 31501409, 2019). "It should be noted that in tumors, insulin, rather than its action to capture glucose, has a mitogenic effect, since the tumor cells have an insulin-independent glucose uptake mechanism." (PMID 31284513, 2019). "Specifically, APN is a strong inhibitor of the PI3K/Akt/mTOR pathway, being able to reduce tumor cell growth induced by insulin and by other growth factors." (PMID 31212761, 2019). "This study evaluated bioavailability (BA) of various formulations of insulin intranasally delivered with protein transduction domain (PTD) derived from translationally controlled tumor protein." (PMID 31210056, 2019). "On the contrary to delayed proliferation effect, significant insulin influence on migration and proliferation rate of primary tumor derived RCC cells’ was observed in wound healing assay over 3 days." (PMID 30929166, 2019). "Mechanistically, TrxR1 activity in tumor tissues was measured by endpoint insulin reduction assay, and the result indicated that combined treatment significantly decreased the activity of TrxR1." (PMID 31113439, 2019). "While well known for its tumor suppressing function, the miR-34 cluster is increasingly recognized for its impact on adiposity, insulin resistance signaling, and thermogenesis." (PMID 31554925, 2019). "There was a significant promotion in tumor weight in control as well as insulin and FU-only treated animals (p < 0.05 in groups 1 to 3)." (PMID 31719636, 2019). "To better model the migration and invasion of tumor cells in situ, we cultured cells in MatrigelTM to form 3D spheroids and repeated insulin treatments." (PMID 31379747, 2019). "For example, CR can impair cancer cell proliferation by reducing plasma glucose and insulin, which in turn alters expression of cell cycle proteins, modifies tumor suppressor gene function, and disrupts metabolic pathways." (PMID 31293576, 2019). "Future studies of Tmem127 should integrate its tumor suppressor functions with its role in cellular glucose and insulin homeostasis." (PMID 31624249, 2019). "Activation of ERK/MAPK pathways is a key event in cell proliferation and tumor progression, that occurs downstream of pathways associated with several growth factors including EGF, PDGF, VEGF, FGF, and insulin, etc.." (PMID 30651129, 2019). "In the current study, we demonstrate that tumor insulin signaling is dynamically regulated under postprandial conditions." (PMID 31867105, 2019). "The activation of these pathways via circulated insulin stimulates IGF-1/IGF-1R activation that promotes the initial tumor proliferation and growth." (PMID 31831021, 2019).
tumor (continued). "Immunohistochemically, tumour cells stained markedly positive for somatostatin (95%) and insulin (5%); interestingly, staining for the two hormones was restricted to distinct cell populations and not uniform throughout the tumour." (PMID 31592116, 2019). "On the other hand, the leucine tumour-bearing group (WL) maintained the serum insulin levels compared with the control group, being different from the W group." (PMID 30975087, 2019). "CK is the main tag of the simple and glandular epithelium, SYN, CgA, and CD56 are used to identify tumors arising from neural and neuroendocrine tissues, and positivity for insulin provides tumor-specific confirmation of the disease." (PMID 32009878, 2019). "The metabolic environment of the tumor is determined by the supply of energy and nutrients and by many critical metabolic regulators: of which insulin and the IGFs play a central role." (PMID 30809194, 2019). "We found that chronic exercise at moderate intensity and low frequency, beginning at 30 days old, was able to attenuate tumor growth and reduce insulin secretion in Walker 256 tumor-bearing adult (90 days old) rats." (PMID 29867528, 2018). "In vitro and in vivo studies have shown that endogenous and exogenous insulin can stimulate tumor promotion via INSR and IGF1R." (PMID 29486734, 2018). "Insulin, as an inducer of nitric oxide that inhibits complex II, increased both tumor oxygenation and radioresponse in a liver and fibrocarcoma mouse tumors, with more tumor growth delay than carbogen breathing (95% O2, 5% CO2)." (PMID 30337872, 2018). "Aerobic exercise training and tumor cell inoculation affected fasting insulin levels in different manners." (PMID 29867528, 2018). "We found that tumors were highly infiltrated by macrophages (F4/80+, CD68+, CD206+) that surround proliferating tumor cells (Ki67+), which also express phosphorylated/activated insulin/IGF-1 receptors." (PMID 29367764, 2018). "Aerobic training significantly reduced fasting glucose before tumor cell inoculation (p < 0.0001) and insulin levels (p < 0.01) in exercised rats compared to sedentary rats." (PMID 29867528, 2018). "The clinical presentation of functioning tumours depends on the peptide hormone being secreted such as insulin, gastrin, glucagon, vasoactive intestinal peptide (VIP) and somatostatin." (PMID 31447997, 2018). "Pro-inflammatory (such as IL-6 and TNF-α) and proliferative (like leptin and insulin) factors are considered as tumor growth favoring molecules." (PMID 29568521, 2018). "Both reports demonstrated that tumours secrete high levels of imaginal morphogenesis protein-Late 2 (ImpL2), a secreted insulin-signalling antagonist that functions by direct binding to Dilp2." (PMID 29725601, 2018). "Another signaling pathway contributing to generating proliferative responses in both normal and tumor thyrocytes is the insulin/IGF axis." (PMID 30513575, 2018). "This information is very important, because during tumor growth and cell proliferation, weak pancreatic insulin secretion is present." (PMID 29867528, 2018). "Attributed to the antidiabetic properties, metformin reduces circulating glucose and insulin, resulting in a decrease in cell proliferation and invasion; this is particularly effective in tumor with high expression of insulin receptors, such as breast cancer." (PMID 30337872, 2018). "INS is an important metabolic hormone and is responsible for anabolic signals that promote tumor development." (PMID 30774817, 2018). "Nuciferine, a natural alkaloid from the lotus leaves, have been reported to exert multiple beneficial effects, in vivo and in vitro, such as anti-tumor and insulin stimulatory effects." (PMID 30360404, 2018). "Although the insulin signaling pathway is known to be responsible for tumor initiation, it insufficiently contributes to hepatocarcinogenesis by itself." (PMID 30477453, 2018).
tumor (continued). "We recommend using a 28-gauge insulin syringe for the tumor injection, though a smaller gauge syringe is certainly acceptable as well." (PMID 29903803, 2018). "After insulin injection, glucose concentrations were decreased in the tumor-bearing sedentary rats at 15, 30, 45, and 60 min compared to sedentary rats (p = 0.001)." (PMID 29867528, 2018). "Body weight (BW), food intake, plasma glucose, insulin levels, and peripheral insulin sensitivity were analyzed before and after tumor cell inoculation." (PMID 29867528, 2018). "Multiple mechanisms are involved, as increased glucose uptake by insulin-sensitive tissues and by the tumor itself, decreased hepatic glucose production, and suppressed insulin and C-peptide levels." (PMID 30210734, 2018). "Tumours retain sensitivity to insulin signalling due to the overexpression of insulin receptor, as a result of elevated expression of Wg." (PMID 29725601, 2018). "Fasting levels of glucose, insulin, glycohemoglobin and selected IR-related and tumor-derived markers were measured." (PMID 29113405, 2017). "In prospective studies, higher circulating insulin and C-peptide levels have been associated with CRC risk, angiogenesis, tumor growth, and anti-apoptosis." (PMID 29070017, 2017). "The tracer displays high specificity for DPP6 and its in vivo properties were validated in mice xenografted with either human insulin secreting cells or a neuronal derived tumour that spontaneously expresses DPP6." (PMID 29123178, 2017). "Tumor promoting activity of insulin can be mediated by insulin receptor (INSR) as well as cross-activation of the insulin-like growth factor 1 receptor (IGF1R) family, resulting in activation of downstream signaling cascades." (PMID 28038446, 2017). "Insulin is known to have mitogenic and pro-survival effects, with tumour cells often expressing high levels of the insulin receptor." (PMID 28444639, 2017). "Second, as a result of poor glycemic control, hyperglycemia can induce elevated levels of insulin and insulin-like growth and inflammatory factors, which can directly augment tumor progression." (PMID 28774279, 2017). "The stimulation of MDA-MB-435 + E-cad cells with insulin or IGF1 decreased the bisecting N-glycans expression on E-cadherin which consequently up-regulated mesenchymal markers with the enhancement of tumour cell invasion." (PMID 28880250, 2017). "Although insulin is thought to work as a tumor promoter or progressor via its effect on cell proliferation, additional studies in other animal models are needed to examine the potential of insulin as a tumor initiator." (PMID 28903776, 2017). "Its contribution towards disturbed insulin secretion, incretin effect, and consequential lowered β-cells survival was enriched by the molecular link with major tumor suppressor gene." (PMID 28194257, 2017). "α-Klotho acts as a tumor suppressor by inhibiting insulin/IGF-1 signaling in breast cancer, lung cancer, pancreatic cancer, gastric cancer, liver cancer, colon cancer, and ovarian cancer." (PMID 29250031, 2017). "Our data support a bidirectional relationship between dysregulated/imbalanced glucose/insulin metabolism and BCa, as tumor- and IR-markers are correlated with the impairment of glucose/insulin metabolism in overweight/obese premenopausal BCa patients." (PMID 29113405, 2017). "Reduced glucose availability and suppression of insulin signaling will produce chronic energy stress on those tumor cells that depend primarily on glucose for growth and survival." (PMID 28250801, 2017). "MEN1/Menin was originally discovered for its tumor suppression function in the pituitary (anterior lobe) and pancreatic islets, which are well-known endocrine organs that secrete prolactin and insulin, respectively." (PMID 28710500, 2017). "Chronic treatment with compounds that possess a high affinity towards the IGF1R, IGF1 and the insulin analogue X10, significantly decreased the tumor latency time." (PMID 28173837, 2017).
tumor (continued). "Usually, insulin promotes proliferation of tumour cells only at higher concentrations than IGF1, possibly since it predominantly acts via type 1 IGFRs." (PMID 28316059, 2017). "Its contribution towards disturbed insulin secretion, incretin effect, and consequential lowered β cell survival was enriched by the molecular link with the major tumor suppressor gene." (PMID 29098064, 2017). "To gain more insight in to overall differences between various insulin analogues in tumor development and progression, we performed RNAseq NGS of 50 tumors (10 tumors per treatment group)." (PMID 28173837, 2017). "FoxO transcription factors can antagonize insulin effects and trigger a variety of cellular processes involved in tumor suppression, longevity, development and metabolism." (PMID 27622707, 2016). "TrxR1 activity in tumor xenografts was measured by the endpoint insulin reduction assay, and the result indicated that EF24 treatment significantly decreased the activity of TrxR1 in a dose-dependent manner." (PMID 26919110, 2016). "The mechanisms are mainly divided into indirect effects by reducing circulating glucose or insulin levels, and direct effects on tumor cells through adenosine monophosphate-activated protein kinase (AMPK)-dependent and AMPK-independent mechanisms." (PMID 27494848, 2016). "Of the other five lesions, two tumors consisted of the insulin-positive tumor cells with less than 0.1 % of the Ki67 index, and three tumors consisted of the glucagon-positive tumor cells with less than 0.1 % of the Ki67 index." (PMID 27572829, 2016). "These hybrids retain high affinity for the IGFs, and a lower affinity for insulin, and are often abundantly expressed in tumor cells." (PMID 27129151, 2016). "This suggests that increased insulin signaling within the tumor is insufficient to promote metastasis." (PMID 27604692, 2016). "Immunohistochemically, the tumor showed strong diffuse expression of chromogranin A, insulin, and glucagon and weak expression of somatostatin." (PMID 27864816, 2016). "Based on the results from a recent window-of-opportunity study, serum insulin, tumour insulin receptor expression, p-Akt, and Ki-67 are potential biomarkers of tumour metformin sensitivity." (PMID 27903276, 2016). "To gain some insight into how prolonged feeding with HFKD promotes tumor growth, we measured the plasma insulin, IGF-1 and growth hormone levels." (PMID 26892894, 2016). "Reduction of circulating levels of insulin is one postulated anti-tumor mechanism of action of metformin." (PMID 26967162, 2016). "At 22 weeks of age (prior to tumor formation) mice were evaluated for diet effects on glucose and insulin tolerance, and blood samples were collected in the fed and fasted states for analysis of circulating nutrients and hormones." (PMID 26924712, 2016). "High IGF-1 and insulin levels in the microenvironment therefore provide a plausible mechanism of carcinogenesis and early tumor growth through anti-apoptotic signaling and metabolic reprogramming mediated by the PI3K–AKT–mTORC1 pathway." (PMID 26878387, 2016). "Despite the fact that metformin can decrease insulin levels and tumour’s cell proliferation, few studies analyse metformin action on skeletal muscle in cachexia models." (PMID 27388367, 2016). "Recently, ARHGAP22 levels have been proposed to determine tumor cell movement and the ARHGAP22 gene has been implicated in a novel insulin-regulated pathway." (PMID 27863428, 2016). "A significant reduction in blood glucose and serum insulin levels was observed in the tumor bearing mice, fed with 2-DG compared to the control mice." (PMID 26135741, 2015). "Our study suggests that downstream signaling from IGFI to HIF1α, which has been the target of many insulin signaling drugs in clinical trials, plays a smaller role in overall tumor growth." (PMID 25884993, 2015). "The insulin/igf1 pathway has been shown to be involved in mammalian regulation of lifespan and tumor growth." (PMID 26647160, 2015).